RPS27A (ribosomal protein S27a)
Diseases named in the same sentence as RPS27A in open-access papers (continued):
Sharing a sentence is not in itself a finding about the gene and the disease.
cancer (27 papers, 2012 to 2025). A tumor composed of atypical neoplastic, often pleomorphic cells that invade other tissues. "Similarly, RPS27A, a core protein identified in association with RNA Translation, could be pivotal in the control of translation initiation, which is a process frequently deregulated in cancer due to its impact on oncogene and tumor suppressor expression." (PMID 40522954, 2025). "An increasing number of studies have shown that RPS27A is involved in regulating the progression of multiple cancer types." (PMID 39667820, 2024). "Accumulating studies indicate that RPS27A participates in regulation of the progression of numerous cancer types." (PMID 33564284, 2021). "Other genes down-regulated by rosiglitazone belonged mainly to two functional groups: “cancer” (RPS27A, SORBS2, STIP1, FGA, FGFR2, SSH3, EPN1) and cell death (SORBS2, STIP1, GAS2, EPN1)." (PMID 22761953, 2012). "The downregulated genes belonged mainly to the “cancer” biofunction (RPS27A, HNRNPA1, STIP1, and TFDP1)." (PMID 22619672, 2012). "In addition, polyamines upregulated the expression of five ribosomal proteins, particularly RPS27A, RPL36A, and RPL22L1, which are associated with cancer malignancy." (PMID 40617352, 2025). "Similarly, the core proteins of NXF1 and NCBP2 in the Ubiquitin Mediated Proteolysis pathway, and RPS27A as a core protein in RNA Translation pathway, were also drive genes of the two cancers." (PMID 40522954, 2025). "The hub genes in modules with high correlation, such as ZAP70, RPS27A, GRP1, SLC39A1, APOBEC3G, and GZMA, could provide insights into the molecular mechanisms underlying cancer progression." (PMID 40395456, 2025). "RPS27A is highly expressed in various cancers and virus-infected liver tissues." (PMID 41303371, 2025). "We also found that RPS27A was significantly elevated in AA-treated tissues and human cancer." (PMID 37888706, 2023). "A study shows that ApoM may inhibit CRC development, while another study suggests that the high expression of ApoM in CRC cells promotes cancer cell proliferation and suppressed apoptosis via increasing the expression of ribosomal protein S27A (RPS27A)." (PMID 36506554, 2022). "The most significant biological functions and pathways of RPS27A enrichment were subsequently investigated with gene set enrichment analysis (GSEA), and integration of TCGA and GTEx database analyses revealed that RPS27A was significantly expressed in most cancer types." (PMID 34796111, 2021). "Cancer-related transcripts of AKR1C2, TPT1 and RPS27A were also down-regulated by AZD3355 in phHSCs." (PMID 34675338, 2021). "Although this study mainly focused on cancer rather than bone diseases, it revealed the regulatory role of RPS27A on macrophage polarization, and macrophage polarization plays a key role in bone remodeling." (PMID 41459514, 2025). "Similar results were also observed in AGO1, RPS27A, SP1, and ETS2 of several cancers." (PMID 35911954, 2022).
tumor (13 papers, 2019 to 2025). "RPS27A expression was measured in tumor and corresponding tumor-adjacent tissue specimens from 46 CRC cases using qPCR." (PMID 33564284, 2021). "Next, we hypothesized that TRIM13 might act as a tumor suppressor gene by ubiquitinating and degrading RPS27A, ultimately attenuating the proliferation and metastasis of LC cells." (PMID 39667820, 2024). "In addition, the inhibitory effects of TRIM13 overexpression on tumor volume and weight were partially blocked by RPS27A overexpression." (PMID 39667820, 2024). "Silencing RPS27a inhibited tumor formation (volume and weight) in vivo." (PMID 35073964, 2022). "Analysis of clinicopathological parameters illustrated that the expression of RPS27A in tumor tissues ≥ 6.0 cm was remarkably lower in contrast with that in tumor tissues < 6.0 cm and was remarkably lower in T3/4 stage patients in contrast with that in T1/2 stage patients (P < 0.01)." (PMID 33564284, 2021). "Ribosomal protein S27a (RPS27A) expression in CRC and tumor-adjacent tissues was detected by qPCR, and its correlation with clinicopathologic characteristics was explored." (PMID 33564284, 2021). "The results of WGCNA showed that the turquoise and blue modules, which are highly related to the eutopic endometrial cell group and the ectopic endometrial cell group, all contained tumor related genes, such as UBC, UBA52, RPS27A, PIK3CB, IRS1, and CEACAM1." (PMID 33868805, 2021). "Furthermore, we examined the expression of RPS27A in tumor and corresponding tumor-adjacent tissue specimens from 46 CRC cases and found that RPS27A expression in tumor tissues was significantly higher than in tumor-adjacent tissues." (PMID 33564284, 2021). "A549 cells with stable knockdown of RPS27a and negative control were injected into the left forelimb muscle in female BALB/c nude mice to explore the effects of RPS27a in cell proliferation and apoptosis; tumor nodules were harvested 47 days after injection." (PMID 35073964, 2022).
infection (4 papers, 2016 to 2026). The state of being infected such as from the introduction of a foreign agent such as serum, vaccine, antigenic substance or organism. "Among these, ribosomal protein RPS27A was validated to interact with PA and to support viral replication during early infection in this study." (PMID 41902225, 2026). "We investigated the level of RPS27a, p-STAT3 and STAT3 after infection with pcDNA3.1-STAT3." (PMID 26942564, 2016).
neurodegenerative disease (2 papers, 2020 to 2022). A disorder of the central nervous system characterized by gradual and progressive loss of neural tissue and neurologic function. "RPS27A might act as a controller of microglia activation in triggering neurodegenerative diseases." (PMID 36405716, 2022).
neurological diseases (1 paper, 2025). "Recently, research found RPS27A was identified as a regulatory gene that could induce microglial activation by regulating cytokine-mediated signaling cascades, thereby contributing to neuroinflammation and progression of neurological diseases." (PMID 41020849, 2025).
RPS27A also shares sentences with these, for which no sentence is quoted: colorectal cancer (5 papers); colon carcinoma (4); Parkinson disease (3); COVID-19 (2); prostate carcinoma (2); amyloid diseases (1); connective tissue disease (1); Diamond-Blackfan anemia (1); Down syndrome (1); Fanconi anemia (1); Huntington disease (1); hypercoagulation (1); Hyperglycemia (1); immune diseases (1); kidney cancer (1); myocardial infarction (1); myocardial ischemia (1); osteosarcoma (1); Sepsis (1).